CXCL2 (C-X-C motif chemokine ligand 2)
Diseases named in the same sentence as CXCL2 in open-access papers (continued):
Sharing a sentence is not in itself a finding about the gene and the disease.
tumor (continued). "CXCR2+ MDSCs were recruited to CXCL2- and MIF-expressing human bladder tumors and those tumor-associated MDSCs exhibited stronger suppression of T cells than the counterpart cells from the peripheral blood of cancer patients or healthy donors." (PMID 38786066, 2024). "It indicated that Fn activated NF-κB p65 signaling and promoted an upregulation of CXCL2 expression in tumor tissues." (PMID 38637499, 2024). "Recruitment and education of Gr1+CD11b+ cells in the TME, particularly through the chemokines CCL2, CXCL1, and CXCL2 or IL-33, are considered critical steps for their contribution to tumor progression and metastasis." (PMID 38236642, 2024). "Meanwhile, IL-17 stimulated ESCC tumor cells to release more CXC chemokines CXCL2 and CXCL3, which are involved in neutrophil migration." (PMID 39906741, 2024). "Accordingly, Th2 cells are implicated in tumor promotion, similarly to monocytic and granulocytic MDSC attracted by MIP-2α/CXCL2." (PMID 38338661, 2024). "Since the tumor-suppressive activity of PRSS35 appeared to depend on the in vivo microenvironment, we focused our study on CXCL2 as a candidate substrate, given its well-established role as a chemokine in the tumor immune microenvironment." (PMID 36934105, 2023). "This is the major receptor involved in MDSC infiltration to the tumor site after binding with its ligand, CXCL1 or CXCL2, produced by the tumor cells." (PMID 37513979, 2023). "The Lin−/c-Kit+/Sca-1+/CD34+ cells from the spleen of tumor-bearing animals expressed a unique inflammatory gene signature, including Tnf, Cxcl2, Nfkbiz, Nfkbia, compared to control BM (CBM) cells or tumor-bearing BM (TBM) cells." (PMID 37134077, 2023). "To further test the function of CXCL2 on the tumor microenvironment and neutrophil polarization, we plan to conduct additional in vivo experiments." (PMID 37540227, 2023). "In the RM-9 tumor model, radiation increased mRNA levels of CXCL2, CXCL3, and CXCL7 at 24 h post-treatment and the protein levels of CXCL1 and CXCL2 at 24 h and 48 h post-treatment." (PMID 38067390, 2023). "A recent study has indicated that YTHDF1 is highly expressed in BRCA tumor tissue, creating a “cold” tumor microenvironment by suppressing the release of pro-inflammatory cytokines Ccl7, Il-17rb, Sell, Cxcl2, and Tnfsf4 in BRCA cells." (PMID 38202722, 2023). "MiR-648 is predicted to regulate 3 feature genes (DDIT3, CXCL2, and STAT3) and has been linked to inhibiting tumor development and overcoming chemotherapy resistance." (PMID 37422588, 2023). "Chronic stress promotes CXCL2/CXCL3 secretion of tumor cells, induces CXCR2 expression of myeloid cells, and thus facilitating spleen myeloid cells movement into tumor tissue through the CXCL2/CXCL3-CXCR2 axis." (PMID 36707854, 2023). "Apoptotic tumor cells can release chemokines CXCL1/CXCL2, recruit neutrophils in peripheral blood and induce them to change into N1‐type neutrophils with killing activity, thus completely removing tumor cells." (PMID 35861052, 2023). "However, CXCL2 may be associated with M2 macrophages and pro-tumor reactions." (PMID 37686093, 2023). "Previous studies in the Ptenpc−/−; Trp53pc−/− tumor model have shown that the education of TAMs is mainly governed by the chemokine CXCL2, which mediates the M2 polarization." (PMID 37055829, 2023). "CXCL2, an immune-related chemokine whose regulatory mechanism is related to DNA methylation, was significantly down-regulated in tumor tissues, and tumors with higher CXCL2 expression contained more multiple tumors than those with lower expression." (PMID 37020540, 2023). "CXC motif chemokine ligand 2 (CXCL2) released by tumor cells, which in turn activates CXC chemokine receptor 2 (CXCR2), and IL-6, IL-8, and IL-1β recruit tumor-infiltrating MDSCs inducing epithelial–mesenchymal transition (EMT) and metastasis." (PMID 36831498, 2023). "We found that many myeloid cell markers were highly expressed in hybrid tumor cells, including Ly6e, Ly6c2, Ccl2, Nos2, Cxcl1, and Cxcl2." (PMID 37138326, 2023).
tumor (continued). "In contrast, in CALB1-expressing tumors, transcription of the same mediators was minimal in cancer cells and instead was found in myeloid cells (CXCL2, CXCL8) and/or tumor-associated fibroblasts (CXCL5, CXCL6)." (PMID 37192000, 2023). "In the case of this chemokine, in almost every type of tumor, if there was a positive correlation between CXCL2 expression and the count of M2 macrophages, there was also a negative correlation between the expression of this chemokine and the count of MDSCs." (PMID 37686093, 2023). "Cytokine array analysis of CM derived from CD26− and CD26+ NFs co-cultured with tumor cells revealed that the co-culture of CD26+ NFs and tumor cells released more CXCL2 and CXCL12 than the co-culture of CD26− NFs and tumor cells." (PMID 36635273, 2023). "VSSP administration following castration significantly reduced tumor volume and tumor weight, a result comparable to CXCL2 inhibition (αCXCR2)." (PMID 37055829, 2023). "CXCL2 can be expressed in neutrophils and tumor cells (also expressed in the MOSE-LTICv) and has been correlated with metastasis and lower survival." (PMID 38264656, 2023). "In the second half of our observation period, the CXCL2 secretion decreases, possibly showing a re-educational effect on the tumor microenvironment coming from the spheroid’s interaction with the rat brain slice cells." (PMID 38069130, 2023). "Due to the hypoxic conditions in tumor, tumor cells express more neutrophil-associated chemokines (CXCL1, CXCL2, and CXCL5) and HMGB1 to rapidly recruit neutrophils." (PMID 38023616, 2023). "Here the authors show that PRSS35 inhibits HCC progression through proteolytic depletion of CXCL2 and subsequently decreased neutrophil recruitment to tumours." (PMID 36934105, 2023). "The activation of CXCL2 and its associated receptor CXCR2 by KRAS signaling is thought to suppress immune response and promote tumor proliferation." (PMID 36033462, 2022). "Similar to CXCL1, CXCR2 inhibition decreases the CXCL2-induced neovascularization and tumor progression." (PMID 35954156, 2022). "CXCL1 and CXCL2, highly expressed in several tumor cells, increase the generation of monocytic MDSC that inhibits T cell proliferation." (PMID 35163097, 2022). "CXCR2, the CXC receptor expressed by neutrophils, can bind with its ligand chemokine family (CXCL1, CXCL2, CXCL3, CXCL5, CXCL7, and CXCL8) to recruit neutrophils to the TME and participate in the mobilization of tumour-associated neutrophils." (PMID 36743929, 2022). "A striking reduction in a CXCL2-defined population was seen in tumor endothelial cells (TEC) which showed little recovery after chemotherapy." (PMID 36253784, 2022). "It is believed that malignant tumor cells can secrete chemokines (CCL2 and CXCL2) to recruit macrophages and MG, which gather around tumor cells, thereby promoting tumor formation and evading immune cell attack." (PMID 35693633, 2022). "KRAS signaling is also thought to activate CXCL2 and its associated receptor CXCR2 resulting in suppressed immune response and tumor proliferation." (PMID 36033462, 2022). "Our previous study showed that lung metastases were a group of mesenchymal tumour cells that secreted CXCL2 to attract M2 macrophages." (PMID 35541899, 2022). "We found that lung metastatic tumours secreted significant CXCL2 chemokines and were infiltrated by a large number of M2-type macrophages." (PMID 35541899, 2022). "At present, there is a relative dearth of studies exploring the role of CXCL2 in the tumor immune microenvironment of LUSC." (PMID 35912252, 2022). "The results revealed that when the prognostic indicator was OS, high grade residual tumor, metastasis, positive margin status, high expression of HELLS and STMN1, low expression of EPAS1, CXCL2, NQO1, IL6 were associated with poor prognosis." (PMID 34982796, 2022). "Mesenchymal tumour cells attracted infiltrating M2 macrophages by secreting CXCL2, which led to tumour invasion, metastasis and proliferation." (PMID 35541899, 2022).
tumor (continued). "There was a significant relationship with tumor stage in the group of CXCL2, CXCL10 and CXCL11 (P < 0.05)." (PMID 35181719, 2022). "Next, we analyzed MDSC chemotaxis-related genes, including Cxcl1, Cxcl2, Cxcl5, and Cxcl12 in tumor tissues." (PMID 34976216, 2022). "Neutrophils are recruited to tumors mainly by ELR+-CXC chemokines produced by tumor cells (e.g., CXCL8, CXCL5, and CXCL6) and by neutrophils themselves (e.g., CXCL2) or by other cells of the tumor stroma." (PMID 35158948, 2022). "Intriguingly, Ding and the colleague revealed that CXCL2 expression was down-regulated in HCC and overexpression of CXCL2 inhibited tumor cell proliferation and promoted apoptosis." (PMID 36276119, 2022). "A recent study reported that elevated CXCL2 in the tumor microenvironment promoted the recruitment of myeloid-derived suppressor cells and was correlated with poor prognosis in patients with bladder cancer." (PMID 36276119, 2022). "TRPM2 expression is increased in tumor cells undergoing epithelial-to-mesenchymal transition, thus leading to increased production of CXCL2 by tumor cells and neutrophil recruitment to tumor sites." (PMID 36514901, 2022). "CXCL1 and CXCL2 chemokine gradients in melanoma-bearing mice induced neutrophil recruitment and tumor angiogenesis." (PMID 33603130, 2022). "Once in the site, MDSCs stimulate the migration of tumor cells by secreting TNFα, CXCL2, TGFβ, IL-6 and CCL2." (PMID 35158779, 2022). "CXCL1 and CXCL2 produced by tumour cells can promote the generation of monocytic myeloid-derived suppressor cells." (PMID 35468838, 2022). "Chemokine CXCL2 is a small secreted protein with a Glu-Leu-Arg (ELR) motif that binds to CXC chemokine receptor 2 (CXCR2) to promote tumor angiogenesis and endothelial cell survival." (PMID 36276119, 2022). "We found canine OSCC had increased CXCL2 expression compared to normal oral mucosa, and in “T-cell high” versus “T-cell low” tumor samples." (PMID 36698398, 2022). "We reanalysed the results of the public database and found that the expression of CXCL2 in lung metastatic tumours was significantly higher than the in situ tumours." (PMID 35541899, 2022). "In order to validate this assumption, the cytokines for neutrophil recruitment, including CXCL1 and CXCL2, were examined in the cisplatin-treated tumor cells." (PMID 35784745, 2022). "A recent report suggests that miR-532-5p, a tumor-suppressor miRNA, negatively regulates CXCL2 in liver cancer cells." (PMID 35954156, 2022). "We analysed the pathological sections of patients and found that SNAIL promoted EMT, and the transformed mesenchymal tumour cells secreted CXCL2, which promoted the infiltration of macrophages and led to the migration of tumour cells." (PMID 35541899, 2022). "After EMT, tumour mesenchymal cells acted on M2 macrophages and tumour cells by secreting CXCL2 and inducing the migration of tumour cells, which led to lung metastasis." (PMID 35541899, 2022). "IL-8 binds to its receptor CXCL1/CXCL2 and promotes angiogenesis, proliferation, and the invasion of tumor cells." (PMID 35892729, 2022). "Tumour mesenchymal cells secreted CXCL2 to attract M2 macrophage infiltration and promote the proliferation and migration of tumour cells." (PMID 35541899, 2022). "As expected, the results of TCGA and GEO dataset indicated that CXCL2 was significantly upregulated in tumor tissues." (PMID 36281171, 2022). "Based on previous studies, we preliminarily found that SNAIL promoted EMT transformation, and transformed mesenchymal tumour cells mediated M2 macrophages to affect tumour migration and proliferation by secreting CXCL2." (PMID 35541899, 2022).
tumor (continued). "The interaction analysis between CXCL2 and immune system further indicated that CXCL2 expression was positively correlated with lymphocytes, including neutrophils and macrophages, especially the M1 macrophages (anti-tumor)." (PMID 36276119, 2022). "CRC treatment with chemotherapeutic agents induces the synthesis of cytokine TNF-α, which in turn triggers the paracrine release of CXCL2 and results in tumor promotion and chemo-resistance." (PMID 35954156, 2022). "TISIDB algorithm indicated the positive correlation between CXCL2 expression and tumor-infiltrating immune cells, including neutrophils and macrophages." (PMID 36276119, 2022). "The roles for the chemokines CXCL1 and CXCL2 in tumor promotion has been mentioned in many studies, such as promoting epithelial-mesenchymal transition (EMT), invasiveness, metastasis, and cell survival under chemotherapy." (PMID 36411463, 2022). "The LILRB3 cluster also contained CXCL2; the CXCL2-CXCR2 axis helps in the recruitment of tumor-associated neutrophils (TANs)." (PMID 36134663, 2022). "The classical example is the 4T1 breast cancer cells that secrete high levels of G-CSF/GM-CSF and CXCL2 that induce the production of both anti-tumor and pro-tumor neutrophils." (PMID 34572138, 2021). "In the tumor stroma, CAFs secrete the cytokines CXCL1 and CXCL2 as well as the interleukin-6, which promote angiogenesis and tumor progression." (PMID 33806312, 2021). "Accordingly, exposure to CXCL2 or to the supernatant of SCC VII or 4T1 tumor cells induced a significant increase in the surface expression of CXCR4 on neutrophils isolated from the peripheral blood of wild-type (WT) mice." (PMID 34876407, 2021). "Tumor-promoting genes such as CXCL2 and LIF, as well as PDL1, a blocker of T-cell-based immune responses were downregulated." (PMID 33859739, 2021). "The mixture of HVJ-E and CXCL2 plasmid DNA succeeded in enhancing CXCL2 expression in the tumor mass and displayed anti-tumor activity by enhancing CTL activity against cancer cells, which resulted from the accumulation of N1-type TANs." (PMID 33575480, 2021). "CXCL2 is reported to promote tumor cell migration through the induction of M2-like macrophage polarization." (PMID 34122424, 2021). "Gold standard therapy temozolomide (TMZ) is known to induce upregulation of IL8/CXCL2/CXCR2 signaling that promotes tumor progression and angiogenesis." (PMID 34681839, 2021). "A study of 69 patients with GC demonstrated that the concentration of CXCL2 in the peripheral and tumor drainage blood was significantly higher than that in patients without recurrence." (PMID 34252149, 2021). "The same study further showed that the chemokines binding to CXCR2 (e.g., CXCL1 and CXCL2) were responsible for BM-neutrophils’ extravasation into the circulation and for their further migration into the tumor." (PMID 34680231, 2021). "It is curious that HVJ-E alone increased N1-type neutrophils in the lung, while CXCL2 plasmid DNA failed to accumulate neutrophils in the lung even though both HVJ-E and CXCL2 plasmid DNA increased neutrophils in primary tumor masses." (PMID 33575480, 2021). "Studies have shown that the high expression of inflammatory chemokines ligand 1 (CXCL1) and ligand 2 (CXCL2) is closely related to tumor invasion, metastasis and poor prognosis." (PMID 34630121, 2021).
tumor (continued). "Both NDN and LDN were found to migrate in response to CXCL1 and CXCL2 exposure, and co-infiltrate the tumor site ex vivo and in vivo, although LDN migration into the tumor was higher than NDN." (PMID 34680231, 2021). "In BCa, tumor cells are implicated in macrophage recruitment via the secretion of CCL2 and MIF/CXCL2." (PMID 34572939, 2021). "The anti-tumor effect of the combination therapy using CXCL2 plasmid DNA and HVJ-E was enhanced by anti-PD-1 antibody treatment." (PMID 33575480, 2021). "Neutrophils bear receptors for a number of neutrophil chemokines, including CXCL1 and CXCL2, that are formed following surgical stress but are also expressed on some tumor cells." (PMID 34899751, 2021). "When CXCL2 protein expression was examined in the tumor mass, CXCL2 was detected in tumors by both pCXCL2 and C/H, with C/H resulting in expression levels more than twice as high." (PMID 33575480, 2021). "Then, to examine the effect of CXCL2 cDNA on tumor suppression when combined with HVJ-E, we compared C/H with the combination of empty plasmid vector, pCY4B, and HVJ-E (pCY4B/H)." (PMID 33575480, 2021). "Our data showed that gefitinib-treated TNBC cells exhibited enhanced production of proinflammatory cytokines/chemokines such as IL-6, IL-8, and CXCL2, hence increasing the number of tumor-infiltrating immune cells including IL-26-producing cells in the TME." (PMID 34021125, 2021). "OmAd promoted GC growth in a humanised omental adipose tissue model using NSG mice, but silencing CXCL2 in OmAd cancelled OmAd-induced tumour growth." (PMID 32439934, 2020). "Snail on the other hand was found to modulate the secretion of chemokines, such as CXCL2, resulting in the increased infiltration of neutrophils into the tumor micro-environment." (PMID 33381110, 2020). "These cells, through the release of CXCL2 in the microenvironment, participate in the building and stabilization of new tumor vessels." (PMID 33066172, 2020). "CXCL2 secreted from omental adipocytes stimulates primary GC tumours through AKT phosphorylation of GC cells, which directly promotes GC growth and invasion." (PMID 32439934, 2020). "CXCL2 significantly promotes tumor migration and invasion, whereas overexpression of CXCL2 inhibits tumor growth and promotes apoptosis." (PMID 33401247, 2020). "Upregulation of Ptgs2 and Cxcl2 was confirmed in additional KPC tumor-derived B cells and was also observed in orthotopic B cells." (PMID 30972056, 2019). "Our recent study demonstrated a novel role of two chemokines, CXCL1 and CXCL2, in promoting monocytic MDSCs (mo-MDSCs) generation by favoring the differentiation of bone marrow cells under tumor conditions." (PMID 31395859, 2019). "(A) Ki-67 positive AMs, (B) Cxcl2 expression in AMs, (C) Cd274 mRNA expression in Epcam+ tumor cells from lungs of control (normal) and tumor bearing CCSP-rtTA; TetO-EGFRL858R mice in the absence (−) and presence (+) of erlotinib for 2 weeks." (PMID 31291990, 2019). "CXCL1 and CXCL2 gradients are found in tumor-bearing mice, low level of chemokine is found in bone marrow (BM) and high level in the tumor." (PMID 31799175, 2019). "LPS stimulation of tumor hepatocytes further enhanced the expression of inflammatory cytokines and chemokines Ccl2, Cxcl1, Cxcl2, Tnfa, and Il6." (PMID 30990169, 2019). "The Snail-expressing cancer cells secrete increased levels of CXCL5 and CXCL2 to recruit more pro-tumoral neutrophils to the tumor, creating a positive amplifying loop to facilitate tumor growth." (PMID 31474975, 2019).